BLM (BLM RecQ like helicase)
Diseases named in the same sentence as BLM in open-access papers (continued):
Sharing a sentence is not in itself a finding about the gene and the disease.
leukemia (9 papers, 2013 to 2026). A malignant (clonal) hematologic disorder, involving hematopoietic stem cells and characterized by the presence of primitive or atypical myeloid or lymphoid cells in the bone marrow and the blood. "Overexpression of BLM and RAD51 facilitates HRR and thereby causes resistance of BCR/ABL-positive leukemia cells to DNA damaging drugs." (PMID 38421735, 2024). "Amongst pluripotency genes, we have identified cancer genes (IDH2, NCOA2, IKZF1, BLM) which are already described as being involved in leukemia." (PMID 37174060, 2023). "Several genes that we identified included IDH2, NCOA2, IKZF1 and BLM described as being involved in leukemia." (PMID 37174060, 2023). "BLM haploinsufficiency led to an early onset of murine T cell lymphoma in response to challenge with leukemia virus." (PMID 35860547, 2022). "Additionally, two studies show that BLM modification by SUMO plays vital roles on the induction of repair foci as well as altering protein subcellular localization to promyelocytic leukemia nuclear bodies (PML-NBs)." (PMID 34606619, 2021). "Finally, we identified two loss-of-function variants (2.1% of the patients) in BLM and PRF1 genes that have been implicated in susceptibility to multiple cancers, mainly leukemias and lymphomas." (PMID 31514334, 2019). "Here, we demonstrate that depletion of BLM (phenocopied by the inhibition of MALT1) suppresses the progression of lymphoma and leukaemia by inhibiting MALT1-dependent NF-κB signalling and sensitizing malignant B cells to chemotherapy." (PMID 42156715, 2026).
colon cancer (8 papers, 2017 to 2024). "The BLM variant, c.3254dupT, is novel and seems to be associated with increased risk of breast, endometrial and colon cancer." (PMID 38313678, 2024). "Somatic frameshift mutations in BLM have been identified in colon cancers and gastric cancers with high microsatellite instability." (PMID 35782872, 2022). "This was particularly observed in the Ashkenazi Jews population harboring heterozygous BLM mutation, which displayed a more than a 2-fold increase in colon cancer incidence." (PMID 33777104, 2021). "Interestingly, in the current study we have identified a new homozygous likely pathogenic mutation in the BLM gene in a patient with multiple primary tumors, breast endometrial and colon cancers." (PMID 38313678, 2024). "For the cancer susceptibility genes identified in the cohort that are not involved in LS, we found several genes implicated in the hereditary colorectal cancer landscape: APC, MUTYH, POLE, POLD1, and BLM, as well as genes resulting in an increased risk of colon cancer as CHEK2." (PMID 36232851, 2022). "Several studies in patients with colon cancer have shown an enrichment of deleterious BLM variants." (PMID 35782872, 2022). "Recent reports have suggested that, in multiple cancers, including colon cancer, BLM protein is aberrantly overexpressed, and this occurrence has been linked to poor patient outcome." (PMID 38421735, 2024). "A recent report identified that hypomethylation of BLM promoter at the CpG islands enhanced the BLM expression in colon cancer cells." (PMID 33777104, 2021). "Constitutive phosphorylation of BLM at Serine 502 by Chk1 during interphase stabilizes its levels, preventing its cullin-3-mediated degradation in colon cancer cells." (PMID 33777104, 2021). "Proximal colon tumors showed higher mutation frequencies than distal tumors on TGFBR2 (30.0% vs 2.8%, P < 0.001), ATM (20.0% vs 2.8%, P = 0.020), BLM (25.0% vs 2.8%, P = 0.005), and PTEN (15.0% vs 1.4%, P = 0.032) genes." (PMID 31548566, 2019). "Therefore, this study provides a firm mechanistic basis on how two key HRR proteins, BLM and RAD54, cause resistance to the common chemotherapeutic drugs used for the treatment of colon cancer." (PMID 38421735, 2024). "BLM is overexpressed in colon cancer cells and patients with shorter relapse-free survival." (PMID 38421735, 2024). "Additionally, it has been shown that BLM expression, by both mRNA and protein levels, is increased in colon cancer samples, along with RECQL4, while RECQL1 and RECQL5 expression are significantly decreased." (PMID 35782872, 2022). "Additionally, BLM also alleviated c-Jun degradation by E3 ligase Fbw7α, thus attenuating the proliferation of colon cancer cells in mouse xenograft model." (PMID 33777104, 2021). "Our unpublished in silico analysis with The Cancer Genome Atlas Colon Adenocarcinoma data set revealed that both BLM and RAD54 were highly overexpressed in the colon cancer samples and that their expression pattern was strongly correlated." (PMID 38421735, 2024). "ChIP-Seq analysis and validation revealed increased BLM and RAD54 corecruitment on the MRP2 promoter in camptothecin-resistant colon cancer cells, leading to BLM-dependent enhancement of RAD54-mediated chromatin remodeling." (PMID 38421735, 2024). "To understand whether the 3 key players (MRP2, BLM, and RAD54) were indispensable for reverting chemoresistance in colon cancer, we carried out siRNA-based ablation in xenograft studies using SCID mice." (PMID 38421735, 2024).
colon cancer (continued). "miR-522-3p was found to be highly expressed in colorectal cancer (CRC) tissues compared to adjacent non-tumor tissues and negatively regulates the BLM levels, promoting proliferation of colon cancer cells and thus demonstrating its tumor suppressor function." (PMID 33777104, 2021).
osteosarcoma (8 papers, 2014 to 2024). A usually aggressive malignant bone-forming mesenchymal neoplasm, predominantly affecting adolescents and young adults. "RNAi-mediated shRNA gene silencing allowed for depletion of BLM, which led to inhibition of specific osteosarcoma cells, implicating its potential use in osteosarcoma." (PMID 35782872, 2022). "The several novel variants of ALK, BLM, PTCH1 in this patient might expand the mutational spectrums of the osteosarcoma." (PMID 35057767, 2022). "Importantly, gene mutations in both BLM and RBBP8 are associated with increased risks of tumor formation, including osteosarcoma." (PMID 33519915, 2020).
lung carcinoma (7 papers, 2015 to 2022). "A second study profiling the mutational landscape of lung cancer identified BLM as being one of nine recurrently mutated genes." (PMID 35782872, 2022). "BLM was found to be differentially expressed amongst lung cancer patients and low expression of BLM was significantly correlated with better overall survival." (PMID 35782872, 2022). "Additionally, patients with lung cancer and stomach cancer have inferior overall survival rates when BLM is overexpressed." (PMID 36499126, 2022). "Furthermore, another study showed that a high expression of the BLM gene, a paralog of RECQL4, was associated with poor prognosis in lung cancer." (PMID 36552262, 2022).
lymphoma (7 papers, 2013 to 2026). A malignant (clonal) proliferation of B- lymphocytes or T- lymphocytes which involves the lymph nodes, bone marrow and/or extranodal sites. "High levels of BLM were also found in hematological malignancies such as myeloid leukemia, lymphoma and myeloma." (PMID 36569948, 2022). "Studies using mouse models further demonstrated that haploinsufficiency of BLM led to an early onset of lymphomas and intestinal tumors particularly CRC." (PMID 33777104, 2021). "In particular, exceedingly high levels of BLM have been demonstrated in all of the hematological malignancies such as intense myeloid leukemia, constant lymphocytic leukemia, lymphoma, and different myeloma." (PMID 33777104, 2021). "It is important to note that the hematopoietic system is predominantly affected by the lack of wild-type BLM expression as the frequencies of lymphoma and leukemia in BS are higher than expected, the most common being the T cell lymphoma." (PMID 33777104, 2021).
Immunodeficiency (6 papers, 2018 to 2026). Failure of the immune system to protect the body adequately from infection, due to the absence or insufficiency of some component process or substance. "Similarly, the BLM gene, coding for a DNA helicase involved in DNA repair, has a well-described role in both cancer predisposition and immunodeficiency." (PMID 30443258, 2018). "Defects in BLM thus impair lymphocyte development, explaining the immunodeficiency phenotype." (PMID 30443258, 2018).
pancreatic cancer (6 papers, 2020 to 2023). "Genomic analyses of pancreatic cancer patient samples reveal that expression levels of SETX and BLM correlate with the occurrence of mutational signatures previously associated to BIR." (PMID 35440629, 2022). "Overexpression of BLM, AURKA and PITX1 has previously been linked with poor survival in breast, lung, bladder and pancreatic cancer." (PMID 32899298, 2020). "Lower OS is linked to increased expression of RECQL, BLM, and WRN in pancreatic cancer." (PMID 37626815, 2023). "Except for MSH3, the rest of the germline mutant genes in non-BRCA carriers with TNBC were involved in the HRR pathway, including BLM, PALB2, NBN, RAD51C, and RAD51D, with the mutation rate of 9.26% (5/54), which increased the risk of other cancers, such as PLAB2 for pancreatic cancer." (PMID 33194720, 2020).
bladder cancer (5 papers, 2009 to 2025). "Increased expression of BLM is associated with decreased OS in bladder cancer and reduced DFI in cholangiocarcinoma." (PMID 37626815, 2023). "The K24R mutation or the small compound irinotecan, which targets BLM K24 lactylation, impairs HR repair and alleviates EPI resistance in bladder cancer cells." (PMID 40634292, 2025).
gastric cancer (5 papers, 2017 to 2026). A primary or metastatic malignant neoplasm involving the stomach. "Further investigation showed that the dysregulation of BLM is associated with poor overall survival (OS) for lung and gastric cancer patients and hence led to the conclusion that BLM has the potential to be used as an important prognostic marker for the detection of lung and gastric cancer." (PMID 32704157, 2020). "For example, a recent study reported a correlation between BLM overexpression and poor overall survival in lung and gastric cancer patients." (PMID 36569948, 2022). "Furthermore, Kaplan–Meier survival analysis suggested that high expression of the BLM gene is one of the reasons for the reduced survival of patients with lung or gastric cancer." (PMID 32704157, 2020).
glioblastoma (5 papers, 2021 to 2025). The most malignant astrocytic tumor (WHO grade IV). "The expression of BLM is elevated in many cancers and the highest expression of BLM was reported in glioblastoma." (PMID 37169803, 2023). "miR‐522 has also been reported to be able to boost colorectal tumorigenesis via targeting BLM, accelerate the progression of endometrial carcinoma by inhibiting MAOB, as well as promote glioblastoma cell proliferation by suppressing PHLPP1." (PMID 33369228, 2021).
multiple myeloma (5 papers, 2014 to 2025). "When cell cycle arrest due to ML216 treatment is sustained over time, apoptosis is triggered in all of the cell lines, suggesting that permanent inhibition of BLM causes DNA damage to a level that is lethal for myeloma cells." (PMID 36569948, 2022). "Furthermore, we identified that high BLM expression is associated with a poor outcome in newly diagnosed multiple myeloma patients treated by HDT and ASCT and with resistance to lenalidomide and HDACi." (PMID 33824465, 2021). "We provide evidence that chemical inhibition of BLM by the small molecule ML216 in HMCLs (human myeloma cell lines) leads to cell cycle arrest and increases apoptosis, likely by accumulation of DNA damage." (PMID 36569948, 2022). "The inhibitor has also shown promise in inducing a significant amount of apoptosis in patient-derived primary myeloma cells having aberrant BLM expression as compared to normal bone marrow." (PMID 33777104, 2021).
cholangiocarcinoma (4 papers, 2021 to 2025). A carcinoma that arises from the intrahepatic biliary tree (intrahepatic cholangiocarcinoma) or from the junction, or adjacent to the junction, of the right and left hepatic ducts (hilar cholangiocarcinoma). "For example, distinct peptide mass fingerprints (PMFs) were identified for early versus late recurrence in cholangiocarcinoma (CCA), where peptides such as KNTC1, DCLK1, ALG10, ATR, and BLM were associated with early recurrence, while SERPINA1, TGFB2, and SERPING1 were implicated in late recurrence." (PMID 41008874, 2025).
endometrial carcinoma (4 papers, 2020 to 2024). A malignant tumor arising from the epithelium that lines the cavity of the uterine body. "It was also shown that BLM may be a potential endometrial cancer predisposing gene which is consistent with our findings." (PMID 38313678, 2024). "According to recent research, BLM levels are elevated in a variety of cancers, including lung squamous cell carcinoma, colon adenocarcinoma, endometrial carcinoma, cervical squamous cell carcinoma, and endocervical adenocarcinoma." (PMID 36499126, 2022).
hereditary cancer (4 papers, 2015 to 2023). Malignant neoplasms occurring in families at a rate greater than that expected by chance and caused by germline mutations in a specific gene. "It is also interesting to highlight candidate genes involved in hereditary cancer (BRCA2, BLM, ERCC2, SMARCA4) or connected to inherited CRC, such as Cowden syndrome (SEC23B) and Peutz–Jeghers syndrome (STK11IP)." (PMID 30871259, 2019). "Thus, it may be possible to selectively target familial cancers as the non-cancerous (i.e. normal) cells are expected to harbor a single wild-type copy of BLM or CHEK2, and produce sufficient protein to render these cells resistant to a SL attack." (PMID 26318585, 2015).
mesothelioma (4 papers, 2021 to 2025). A usually malignant and aggressive neoplasm of the mesothelium which is often associated with exposure to asbestos. "An elegant study examining gene-environment links demonstrated that germline BLM variants increase susceptibility to asbestos-related carcinogenesis, leading to mesothelioma, a link first identified in patients with mesothelioma and confirmed in a mouse model." (PMID 35782872, 2022). "Germline BLM deletions have convincingly been shown to increase the susceptibility to asbestos and mesothelioma in clinical, in in vitro and animal studies." (PMID 34948918, 2021).
viral infection (4 papers, 2015 to 2023). "The localization of BLM at sites of viral infection suggests a role of BLM with possibly MRN to process viral DNA ends." (PMID 25906194, 2015). "During viral infection, adenoviruses target multiple aspects of DSB repair, with degradation and/or translocation of MRN components, BLM, DNA Ligase IV and TIP60." (PMID 34960712, 2021). "Further studies of how human DNA damage response proteins like BLM, or Werner syndrome helicase (WRN) which is a HIV-1 cofactor, play a role in viral infection and growth may prove to be informative in the development of anti-viral medicines." (PMID 25906194, 2015).
acute myeloid leukemia (3 papers, 2009 to 2025). Acute myeloid leukemia (AML) is a group of neoplasms arising from precursor cells committed to the myeloid cell-line differentiation. "In acute myeloid leukemia (AML) samples with normal karyotype, high expression of BLM displayed a strong association with poor prognosis, whereas with abnormal karyotype, high expression of BLM associated with better OS." (PMID 33777104, 2021).
anemia (3 papers, 2016 to 2024). A reduction in the number of red blood cells, the amount of hemoglobin, and/or the volume of packed red blood cells. "Additionally, we found a clique that consists of Fanconi anemia (FA) proteins (FANCF, FANCM, FANCG and FANCD2) and a third clique with two FA proteins together with BLM and RMI2." (PMID 38909016, 2024).
colon adenocarcinoma (3 papers, 2020 to 2024). "Interestingly, we also found that BLM expression was significantly higher in some cancers including BLCA (Bladder Urothelial Carcinoma), COAD (Colon adenocarcinoma) and LUSC (Lung squamous cell carcinoma)." (PMID 32704157, 2020).